OR1F12P (olfactory receptor family 1 subfamily F member 12, pseudogene)
Description:
Odorant receptor.
Synonyms: OR1F12; hs6M1-35P; OR1F12Q; OR6-12
Gene: Unprocessed pseudogene on chromosome 6 (28,073,316 to 28,074,233, forward strand). Ensembl gene ENSG00000220721.
Subcellular location: Cell membrane
Pathways (Reactome):
Sensory Perception: Expression and translocation of olfactory receptors